ITLN1 (intelectin 1)
Diseases named in the same sentence as ITLN1 in open-access papers (continued):
Sharing a sentence is not in itself a finding about the gene and the disease.
lung carcinoma (7 papers, 2010 to 2022). "ITLN1 levels were elevated in the pleural fluid of MPM patients compared with the levels seen in lung cancer, tuberculosis, or pneumonia." (PMID 35186726, 2022). "Another study noted a lower level of circulating ITLN1 in Iranian male smokers with lung cancer compared with apparently healthy smokers." (PMID 35186726, 2022). "Overall, survival in lung cancer patients expressing high levels of ITLN1 was found to be significantly better compared to those expressing low levels of ITLN1 (HR-0.76, p = 0.00083)." (PMID 33450975, 2021). "More importantly, recent evidence showed overexpression of ITLN-1 in human malignant pleural mesothelioma, which has potential screening applications in differentiating this disease from lung cancer." (PMID 24358121, 2013). "Pleural effusion with pleuropneumonia tended to contain a little more intelectin-1 than that with lung cancer." (PMID 20628387, 2010). "Pleural effusions of MPM patients contained higher concentrations of intelectin-1 than those of lung cancer patients and tuberculosis patients." (PMID 20628387, 2010). "Pleural effusion of MPM patients contained a higher concentration of intelectin-1 than that of lung cancer patients." (PMID 20628387, 2010). "The pleural effusions of epithelioid-type MPM patients were apt to contain higher concentrations of intelectin-1 than those of lung cancer or tuberculosis patients." (PMID 20628387, 2010). "We, therefore, propose that ITLN1 could be an important prognostic marker in lung cancer and can also be the connecting link between increased BMI and improved lung cancer outcomes." (PMID 33450975, 2021). "Indeed, expression of ITLN1 is high in the healthy lungs compared to other body sites, which seems to be lost in lung cancers." (PMID 33450975, 2021). "Interestingly, ITLN1 (omentin 1) was the only significantly downregulated adipokine in lung cancer compared to healthy lung tissue in all datasets." (PMID 33450975, 2021). "Intelectin-1 was expressed in only 1 of 88 cases of lung cancer, whereas calretinin, CK 5/6, podoplanin, and mesothelin were expressed in about 23%, 44%, 14%, and 40% of lung cancers, respectively." (PMID 22768319, 2012). "ITLN1 is over-expressed in human malignant pleural mesothelioma (MPM) and secreted into pleural effusions, and serves as a biomarker for differentiating from lung cancer." (PMID 25889839, 2015). "Notably, circulating ITLN1 in smokers with lung cancer was not different from that of healthy non-smokers." (PMID 35186726, 2022). "However, the adipocytes and preadipocytes were strikingly higher in the normal tissue compared and found a single adipokine, omentin 1 (ITLN1), to be consistently and significantly underexpressed in lung cancers irrespective of gender, cancer subtype, age and smoking status." (PMID 33450975, 2021). "Importantly, recent evidence shows that ITLN1 is over-expressed in human malignant pleural mesothelioma (MPM) and secreted into pleural effusions, and serves as a biomarker for distinguishing MPM from lung cancer, implicating the emerging roles of ITLN1 in human cancers." (PMID 25965823, 2015).
prostate carcinoma (7 papers, 2011 to 2024). A carcinoma that arises from epithelial cells of the prostate gland. "Patients with gastrointestinal and prostate cancer showed increased levels of circulating ITLN1, whereas gynaecological and breast cancer patients had lower ITLN1 levels than controls." (PMID 37238197, 2023). "Compared with control groups, patients with gastrointestinal and prostate cancer showed increased concentrations of circulating ITLN1, while patients with gynecological, breast, bladder, and renal cancer had lower ITLN1 levels." (PMID 35186726, 2022). "Arjmand and colleagues suggested that prostate cancer patients had significantly higher circulating ITLN1 levels compared with control groups in all the studies included in their review." (PMID 35186726, 2022). "High concentrations of ITLN1 were found in patients with gastrointestinal and prostate cancer compared with control groups." (PMID 35186726, 2022). "In summary, the available literature suggests that circulating ITLN1 is elevated in prostate cancer and reduced in bladder and renal cancer." (PMID 35186726, 2022). "Ectopic expression of ITLN1 into prostate cancer cells results in significantly decreased in vitro cell viability; meanwhile, increased tumorigenicity and in vivo growth are observed in ITLN1 knockdown prostate cancer cells." (PMID 25965823, 2015). "Similarly, a more recent study observed that prostate cancer patients had greater concentrations of circulating ITLN1 compared with individuals with BPH." (PMID 35186726, 2022). "In both studies, circulating ITLN1 was higher in prostate cancer than in BPH." (PMID 35186726, 2022). "The levels of ITLN1 are also dysregulated in prostate cancer." (PMID 35186726, 2022). "Notably, levels of circulating ITLN1 were consistently higher than control groups in gastrointestinal and prostate cancer and lower than control groups in renal, lung, bladder, endometrial, and breast cancer." (PMID 35186726, 2022). "Importantly, Itln1 expression was itself shown to suppress prostate cell growth, and thus Itln1 appears to be an effector of prostate cancer repression." (PMID 21324158, 2011). "Ectopic expression of ITLN1 into prostate cancer cells results in significantly decreased in vitro cell viability; meanwhile, increased tumorigenicity and in vivo growth are observed in ITLN1 knockdown prostate cancer cells, indicating a tumor suppressive role of ITLN1 in prostate cancer." (PMID 25889839, 2015).
colon carcinoma (6 papers, 2010 to 2023). "Supraphysiological ITLN1 also inhibited the proliferation and promoted the apoptosis of colon cancer stem cells in a time-dependent manner." (PMID 35186726, 2022). "Expression levels of LGR5, VSIG4, GZMB, and ITLN1 were tested in colon cancer and adjacent normal tissues via qRT-PCR method." (PMID 36186438, 2022). "Because intelectin-1 mRNA is expressed in normal intestines, we also investigated expression of intelectin-1 in colon cancer." (PMID 20628387, 2010). "The results showed that the expression levels of the ITLN1 and CXCL13 genes in normal tissues were higher than those in colon cancer tissues, and the expression was located in the cytoplasm and cell membrane." (PMID 33579281, 2021). "In this study, we constructed a 6-gene signature (ITLN1, HOXD9, TSPAN11, GPRC5B, TIMP1 and CXCL13) prognostic stratification system based on the colon cancer invasion-related genes, and evaluated the stability and accuracy of the model." (PMID 33579281, 2021). "The box plots suggested that the ITLN1, TSPAN11, CPRC5B, and CXCL13 genes were significantly lowly expressed in the colon cancer samples and the TIMP1 gene was highly expressed in the colon cancer samples in the TCGA cohort." (PMID 33579281, 2021). "In seven patients, colon carcinomas did not express intelectin-1 (data not shown)." (PMID 20628387, 2010). "Thus, colon cancer would not increase the amount of intelectin-1 in a body." (PMID 20628387, 2010). "Thus, the amount of intelectin-1 in a body would not increase because of colon cancer." (PMID 20628387, 2010).
Crohn disease (6 papers, 2019 to 2025). A gastrointestinal disorder characterized by chronic inflammation involving all layers of the intestinal wall, noncaseating granulomas affecting the intestinal wall and regional lymph nodes, and transmural fibrosis. "Genome-wide association studies identified SNPs in ITLN1 that are linked to susceptibility for Crohn’s disease." (PMID 36072603, 2022). "ITLN1 has been identified in the context of multiple human diseases, including Crohn’s disease (CD) where nucleotide variants, associated with increased disease risk, have been identified at the ITLN1 locus." (PMID 36072603, 2022). "ITLN1, a gene present on chromosome 1q23.3, has been identified by genome-wide association studies as a risk locus for Crohn’s disease (CD), a major form of inflammatory bowel disease." (PMID 36072603, 2022). "This European haplotype also contains an ITLN-1 valine-to-aspartic acid coding variant (rs2274907), hypothesized to functionally mediate the Crohn’s disease association." (PMID 38724552, 2024). "Interestingly, the rs4656959 SNP is part of an 84-SNP linkage disequilibrium block (r2 > 0.8) in Europeans, which stretches up- and downstream of ITLN1 and has been associated with Crohn’s disease in GWAS studies." (PMID 38724552, 2024). "Together, these findings suggest that the mucosal transcript level of ITLN1 is unaltered in Crohn’s disease." (PMID 34145348, 2021). "Our data suggest that mRNA transcript and protein abundance of mucosal ITLN1, now confirmed to be goblet-cell derived, is unaltered in the Crohn’s disease samples overall, as well as in samples analyzed according to rs2274907 (A/T, V109D) genotype in both disease and non-disease specimens." (PMID 34145348, 2021). "Thus, ITLN1 was found to be an abundant protein in the small intestine, where expression was comparable in specimens from control and Crohn’s disease biopsies, consistent with mRNA expression data." (PMID 34145348, 2021). "Furthermore, our data indicate that any role(s) of V109D in Crohn’s disease pathogenesis is unlikely due to changes in ITLN1 carbohydrate recognition or protein oligomerization." (PMID 34145348, 2021).
hepatocellular carcinoma (6 papers, 2015 to 2025). A malignant tumor that arises from hepatocytes. "Furthermore, a supraphysiological dose of ITLN1 (1–2 μg/ml) led to the arrest of cell cycling and subsequent apoptosis in hepatocellular carcinoma cell lines." (PMID 35186726, 2022). "In hepatocellular carcinoma (HCC), loss of ITLN1 correlates with aggressive clinicopathological features and poor outcomes, and restoration of omentin signaling—either directly or via lactoferrin-ITLN1 interactions—has demonstrated anti-tumor efficacy in preclinical models." (PMID 41149627, 2025). "•ITLN1 acts as a tumor suppressor in hepatocellular carcinoma (HCC)." (PMID 41218553, 2025). "For hepatocellular carcinoma, research efforts should focus on the prospective validation of ITLN1 as a prognostic biomarker across HBV-, HCV-, and MASLD-related HCC." (PMID 41149627, 2025).
neuroblastoma (6 papers, 2015 to 2025). Neuroblastoma (NB) is the most common solid, extracranial childhood tumor. "In neuroblastoma cell lines and human tumors, increased ITLN1 seemed to have a PI3K/Akt-mediated protective effect by increasing the expression of N-myc downstream-regulated gene 2 (NDRG2) and by reducing tumor volume and metastatic potential." (PMID 35186726, 2022). "Human neuroblastoma cell lines were treated with recombinant ITLN1 protein or stably transfected with ITLN1 expression and short hairpin RNA vectors." (PMID 25889839, 2015). "ITLN1 was proven to exerts a protective influence in neuroblastoma and gastrointestinal tumors." (PMID 41218553, 2025). "Notably, higher ITLN1 expression in human neuroblastoma tumors improved the probability of survival." (PMID 35186726, 2022). "The ITLN1 and NDRG2 transcript levels in NB tissues were positively correlated (correlation coefficient R = 0.291, P = 0.0059), and were inversely associated with the international neuroblastoma staging system (INSS) stages." (PMID 25889839, 2015).
breast carcinoma (5 papers, 2012 to 2025). "Tahmasebpour and colleagues also observed that ITLN1 gene expression was significantly downregulated in breast cancer tissue compared with adjacent normal tissue." (PMID 35186726, 2022). "Three reports examined the circulating levels of ITLN1 in breast cancer patients compared with healthy controls." (PMID 35186726, 2022). "Patients with breast cancer had lower circulating ITLN1 levels in all three studies." (PMID 35186726, 2022). "The right pane focuses on biochemical assay and genotyping for breast cancer (BC) and control groups, featuring pie charts for genotyping of CD295 and ITLN1, highlighted tests like insulin and leptin, and a comet assay with red fluorescent images." (PMID 41221514, 2025).
diabetes (5 papers, 2017 to 2025). "This study was conducted to explore whether SNPs in CD295 (ID rs6700986) and ITLN1 (rs952804) confer risk for metabolic derangements of IR and/or diabetes mellitus (DM) in female BC patients in Egypt." (PMID 41221514, 2025). "One of these studies showed that the adipokine Omentin-1 (Intelectin-1, ITLN1) correlates with diabetes in VAT, while levels of proteins from the endoplasmic reticulum and stress-related proteins are elevated in SCAT." (PMID 40837072, 2025). "Single-nucleotide polymorphisms (SNPs) in the adipocyte-inferred novel cytokine intelectin 1 (ITLN1) remain understudied in connection to CD295 polymorphisms and diabetes mellitus (DM) or a pre-diabetic state, as well as to DNA damage seen in BC." (PMID 41221514, 2025). "Subsequently, correlation analysis revealed a bifurcated adipokine landscape—classical regulators EP, ITLN1, and RBP4 were observed in both datasets, plus LEP in diabetes—maintaining strong positive ties to mitochondrial hubs, signifying a conserved energy–support axis." (PMID 40869253, 2025).
inflammatory bowel disease (4 papers, 2021 to 2023). A spectrum of small and large bowel inflammatory diseases of unknown etiology. "Human ITLN1 is implicated in the etiology of inflammatory bowel disease." (PMID 36072603, 2022).
lung adenocarcinoma (4 papers, 2010 to 2018). A carcinoma that arises from the lung and is characterized by the presence of malignant glandular epithelial cells. "This study indicates that DAB2 and Intelectin-1 are novel positive immunohistochemical markers of epithelioid MM, and should allow for its differentiation from lung adenocarcinoma." (PMID 29538329, 2018). "In this study, we found that intelectin-1 is expressed by about 90% (23/26 cases) of epithelioid-type MPMs and by <5% (1/68 cases) of lung adenocarcinomas." (PMID 22768319, 2012). "Epithelioid-type MPMs, but neither pleura-invading lung adenocarcinomas nor reactive mesothelial cells near the lung adenocarcinomas, are positive for ITLN1 immunostaining, suggesting that ITLN1 is a proper diagnostic marker for MPM." (PMID 25889839, 2015). "A recent study has demonstrated that the positive rates of DAB2 and Intelectin-1 (INLT1) expression were 80% and 76% in epithelioid MM, and 3% and 0% in lung adenocarcinoma, respectively." (PMID 29538329, 2018). "Pleura surface mesothelioma cells expressed both calretinin and intelectin-1 (Figure 3Ac and Ba); in contrast, reactive mesothelial cells on a lung adenocarcinoma-invaded pleura expressed calretinin but not intelectin-1." (PMID 20628387, 2010). "In specimens of eight pleuritis patients with lung adenocarcinoma, no cell expressed intelectin-1 (data not shown)." (PMID 20628387, 2010). "In pleural biopsy-resected tissue, epithelioid-type MPM – but neither pleura-invading lung adenocarcinomas nor reactive mesothelial cells near the lung adenocarcinomas – specifically expressed intelectin-1 protein." (PMID 20628387, 2010). "Epithelioid-type MPM cell lines, but not lung adenocarcinoma cell lines, secreted trimeric intelectin-1." (PMID 20628387, 2010). "On the other hand, intelectin-1 was not expressed in either reactive mesothelial cells or pleura-invading lung adenocarcinoma." (PMID 20628387, 2010). "Malignant pleural mesothelioma cell lines, but not lung adenocarcinoma cell lines, secreted intelectin-1." (PMID 20628387, 2010). "In contrast, four lung adenocarcinomas (ABC-1, RERF-LC-Ad-2, PC-3, and A549), a colon adenocarcinoma (Caco-2), and a prostate adenocarcinoma (DU145) did not express intelectin-1." (PMID 20628387, 2010).
mesothelioma (4 papers, 2010 to 2022). A usually malignant and aggressive neoplasm of the mesothelium which is often associated with exposure to asbestos. "Subsequently, increased expression of ITLN1 was observed in mesothelioma cell lines and epithelioid mesotheliomas." (PMID 35186726, 2022). "The simplicity of assessment using intelectin-1 staining ensures better differential diagnosis than when other mesothelioma markers are used." (PMID 22768319, 2012). "In the present study, we investigated the expression of intelectin-1, a new mesothelioma marker, in normal tissues in the whole body and in many cancers, including MPM, by immunohistochemical analysis." (PMID 22768319, 2012). "Epithelioid-type MPMs were immunostained with antibodies against intelectin-1 or typical mesothelioma markers, such as calretinin, CK5/6, podoplanin, WT-1, and mesothelin." (PMID 22768319, 2012). "In this study, we showed that mesothelioma cells specifically secreted intelectin-1 and that the pleural effusions of MPM patients contained large amounts of intelectin-1." (PMID 20628387, 2010). "In a biphasic-type MPM, only epithelioid-like mesothelioma cells expressed intelectin-1." (PMID 20628387, 2010). "All tested epithelioid-type MPMs were stained with anti-intelectin antibodies; well-differentiated epithelioid-type mesotheliomas near a pleura surface tended to express intelectin-1, whereas a small number of poorly differentiated epithelioid-type mesothelioma produced intelectin-1." (PMID 20628387, 2010). "Therefore, intelectin-1 staining could be useful in diagnosing epithelioid-type MPMs, which account for 50–80% of MPMs, in cases suspected to be mesothelioma." (PMID 22768319, 2012). "Three human mesothelioma cell lines – ACC-MESO-1, ACC-MESO-4, and MEYK4 – secreted 120 kDa trimeric intelectin-1 recognised by these mAbs into the culture supernatant." (PMID 20628387, 2010). "Although immunoreactivity for ITLN1 in epithelioid mesothelioma tumors was very strong, ITLN1 seemed to be absent from other tumors (both mesothelioma and non-mesothelioma) unless they were mucus-producing." (PMID 35186726, 2022). "Mesothelioma cell lines derived from epithelioid-type MPM – ACC-MESO-1, ACC-MESO-4, MEYK2, MEYK4, NCI-H28, NCI-H2052, and NCI-2452 – secreted intelectin-1 detected by anti-intelectin-1 pAb, yet MSTO-211H derived from lung-metastatic site of biphasic MPM did not secrete intelectin-1." (PMID 20628387, 2010). "In a biphasic-type MPM patient, epithelioid-like mesothelioma cells (left side) but not sarcomatoid-like cells (right side) expressed intelectin-1." (PMID 20628387, 2010).